LEP (leptin)
Diseases named in the same sentence as LEP in open-access papers (continued):
Sharing a sentence is not in itself a finding about the gene and the disease.
glioblastoma (continued). "Leptin and its receptor ObR are overexpressed in malignant brain tumours and display a strong positive correlation with histopathological grade, with the highest levels consistently observed in glioblastoma (GBM), a WHO grade IV astrocytic neoplasm." (PMID 41586225, 2025). "In glioblastoma, the leptin–ObR axis actively contributes to tumour metabolism, regulating glutamate and glucose transporters, reinforcing reliance on aerobic glycolysis and glutaminolysis over oxidative phosphorylation, driven by mitochondrial adaptation and dysfunction." (PMID 41586225, 2025). "In addition, LDFI showed to be very effective in abrogating the leptin-promoted proliferation and migration of human glioblastoma cells, U-87 MG and T98G, and in reducing the expression of many leptin-induced target genes." (PMID 34356668, 2021). "Collectively, these data suggest that the Notch signaling pathway could be engaged with the activated leptin signaling in sustaining glioblastoma growth and progression." (PMID 32526957, 2020). "Here, we identified a novel leptin-mediated mechanism that promotes glioblastoma progression." (PMID 32526957, 2020). "Among the various circulating mediators, leptin has gained especial diagnostic and therapeutic interest, although the precise relationship between leptin and glioblastoma biology remains largely unknown." (PMID 33316976, 2020). "Increasing evidence from experimental studies (e.g., glioblastoma C6 cells lines) and some clinical studies have led to randomized-controlled trials incorporating inhibitors of the leptin/ObR axis as adjunctive therapy with established protocols in newly diagnosed and recurrent glioblastoma." (PMID 33316976, 2020). "In addition, VM was found to be more frequently expressed with higher expression of ObR in glioblastoma tissues and higher leptin in patients’ serum, and the co-expression of VM with ObR was further confirmed the importance of leptin in VM formation." (PMID 28938545, 2017). "This review explores the link between leptin and glioblastoma." (PMID 22263109, 2012). "The biological interaction of leptin with Notch signaling pathways was found to be required for glioblastoma multiforme (GBM) development and progression." (PMID 33799880, 2021). "Interestingly, upregulation of adenosine monophosphate-associated protein kinase (AMPK) following metformin administration abrogates the leptin-induced growth and migration of glioblastoma cells, also mediated by downregulation of STAT3 and Akt/PKB serine threonine kinase." (PMID 33316976, 2020). "We found that the expression of leptin and its receptors was significantly higher in human glioblastoma cells, U-87 MG and T98G, than in a normal human glial cell line, SVG p12, and that activation of leptin signaling induced growth and motility in GBM cells." (PMID 32526957, 2020). "The highest levels of leptin and ObR were found in glioblastoma multiforme (GBM), where both proteins were coexpressed with activated forms of serine/threonine protein kinase B (Akt) and signal transducer and activator of transcription 3 (STAT3)." (PMID 21771332, 2011). "VM in glioblastoma tissues was recognized by CD31-/PAS+ immunohistochemical staining and leptin expression in tissues was measured by immunohistochemistry." (PMID 28938545, 2017). "In ObR-positive glioblastoma cell lines LN18 and LN229, leptin stimulates cell proliferation and induces STAT3 and Akt pathways as well as inactivates the cell cycle suppressor Rb." (PMID 21771332, 2011). "In human brain cancer, especially in glioblastoma multiforme (GBM), leptin and its receptor (ObR) are overexpressed relative to normal tissue." (PMID 21771332, 2011). "Significant differences between glioblastoma samples and healthy controls were observed for angiopoietin, follistatin, HGF, IL-8, PDGF-BB, PECAM-1 and leptin, with specificity ranging from 59–81% and sensitivity from 40–88%, while infrared-spectroscopy reached 100% sensitivity and 87.5% specificity." (PMID 33316976, 2020).
glioblastoma (continued). "In case of glioblastomas, not much difference was observed between the cases that showed moderate and strong leptin expression." (PMID 30803210, 2019). "Furthermore, leptin was reported to enhance the migration and invasion of C6 rat glioblastoma cells mainly through the p38 mitogen-activated protein kinase (MAPK) and Nuclear Factor-kB pathway to promote proliferation on human glioblastoma cell lines and to exert pro-angiogenic effects." (PMID 32526957, 2020).
Hepatitis (17 papers, 2004 to 2024). Inflammation of the liver. "Leptin and adiponectin secreted from the adipose tissue have a pro and anti-inflammatory effect on liver inflammation." (PMID 38170037, 2023). "Leptin is one of the most prominent adipokines and binding of leptin to its receptor displayed on KCs can promote fatty acid oxidation and exacerbate liver inflammation and fibrosis in NAFLD." (PMID 37274349, 2023). "Some studies have reported that patients infected specifically by hepatitis C virus (HCV) that suffer from hepatitis presented high serum leptin levels." (PMID 33316927, 2020). "The authors suggest that leptin protects against T cell-mediated hepatitis via modulation of invariant natural killer (iNKT)." (PMID 25098352, 2015). "While some studies have been supported these findings, others have reported low serum leptin levels in post-hepatitis cirrhotic patients." (PMID 15387890, 2004). "Leptin, visfatin and chemerin act as proinflammatory agents and chemotactic factors for immune cells, and thus might be involved in the process of hepatitis." (PMID 35549673, 2022). "Hs-CRP, leptin, and adiponectin were measured in the NAFL patients with regard to liver inflammation." (PMID 33827700, 2021). "The finding appears consistent with a previous study demonstrating that post-hepatitis cirrhotic patients had significantly higher serum leptin levels than healthy control without significant differences in BMI." (PMID 25879666, 2015). "Finally, a neutralizing (both binding of leptin and signalling) nanobody directed against the CRH2 domain in the LR also worsened the clinical outcome of Con A-induced hepatitis." (PMID 25098352, 2015).
left ventricular hypertrophy (17 papers, 2007 to 2024). Enlargement of the LEFT VENTRICLE of the heart. "Leptin levels are positively associated with reduced cardiac contractility, increased myocardial wall thickness and left ventricular hypertrophy." (PMID 34679472, 2021). "We found similar patterns in male gorillas, with high leptin and low adiponectin associated with indicators of left ventricular hypertrophy." (PMID 31242268, 2019). "Leptin seems to exert more actions at cardiac levels because elevated circulating leptin levels are associated with left ventricular hypertrophy in patients with uncomplicated obesity." (PMID 29196758, 2017). "Although the physiological function of leptin is rather contradictory, as it is associated with left ventricular hypertrophy in hypertensive, insulin-resistant men, it also induces direct vasodilatation through distinct endothelial mechanisms." (PMID 25787668, 2015). "Increased plasma leptin has also been shown to predict the development of cardiac failure and is positively associated with the severity of left ventricular hypertrophy." (PMID 20066136, 2008). "In addition, high leptin associates with left ventricular hypertrophy in hypertensive subjects, independently of actual BP levels." (PMID 25061971, 2014). "Evidence from both clinical and experimental studies strongly suggests a link between the development of left ventricular hypertrophy and leptin." (PMID 38256208, 2024). "Improving the BPH/5 maternal obesogenic environment by pair‐feeding the dams, results in reduction of WAT depot mass and heart enlargement in both male and female adult offspring, whilst lowering circulating leptin and left ventricular hypertrophy in females." (PMID 36065848, 2022). "Leptin and its receptor are expressed in the heart, and leptin has been shown to promote left ventricular hypertrophy." (PMID 30424579, 2018). "In this review, we discuss how leptin has been shown to play an antihypertrophic role in the development of left ventricular hypertrophy through in vitro experiments, population-based cross-sectional studies, and longitudinal cohort studies." (PMID 26064110, 2015). "Impaired leptin signaling, as in state of hyperleptinemia, leads to development of left ventricular hypertrophy, and induces chronic oxidative stress in endothelial cells and activates atherogenic process in vitro models." (PMID 26473487, 2015). "As for the event of left ventricular hypertrophy, researchers have been stirring controversy about the role of leptin in this form of cardiac remodeling." (PMID 26064110, 2015). "Conversely, we also examine how leptin may actually promote left ventricular hypertrophy using in vitro analysis and human-based univariate and multiple linear stepwise regression analysis." (PMID 26064110, 2015). "Thus, a number of clinical studies reported a close positive relationship between left ventricular hypertrophy and plasma leptin levels, although such studies do not prove a cause-and-effect relationship." (PMID 38256208, 2024). "Clinical studies demonstrated a positive correlation between serum leptin levels and left ventricular hypertrophy independent of blood pressure values." (PMID 30424579, 2018).
liver cancer (17 papers, 2008 to 2024). An epithelial or non-epithelial malignant neoplasm that arises from the liver. "The inhibition of the ER stress-associated apoptotic pathway contributes to a leptin-induced increase in liver cancer cells." (PMID 33671547, 2021). "Noteworthy, it is suggested that women are subject to a lower HCC risk due to a lower sensitivity to leptin, while increased levels of adiponectin in females protect against liver cancer." (PMID 33316927, 2020). "Through dose-response, we can more clearly explore the relationship between AdipoQ and leptin and liver cancer risk." (PMID 33256658, 2020). "In the absence of the STAT3 inhibitor AG490, leptin-induced malignant behaviors were notably restrained, further confirming the powerful carcinogenic effect of leptin in liver cancer." (PMID 38273295, 2024). "The induction of methionine adenosyltransferases confers the mitogenic property of leptin in liver cancer cells." (PMID 33671547, 2021). "Leptin can also increase the proliferation and the metastatic potential of cholangiocarcinoma cells and has exhibited mitogenic activities on human liver cancer HepG2 cells through the induction of methionine adenosyltransferase 2A and 2β." (PMID 33316927, 2020). "Our results indicated that the leptin levels of liver cancer patients were significantly higher than that of the CFC group, healthy control group, and liver cirrhosis group." (PMID 33256658, 2020). "While the role of IL-6 in promoting function in liver cancer is well documented, less is known about leptin signaling in HCC development." (PMID 30224299, 2018). "Mechanistic delineation of leptin in adipocytes is required to elucidate its relationship with liver cancer initiation." (PMID 27703473, 2016). "Results show that knockdown of either gene inhibits proliferation of liver cancer cells in response to mitogens like leptin." (PMID 24212770, 2011). "Another growth factor known to promote growth and invasive potential of liver cancer cells is the product of the obese (Ob) gene, leptin." (PMID 24212770, 2011). "Leptin has a mitogenic potential in liver cancer cells, which is mediated through the induction of Mat2a and Mat2b genes." (PMID 20808936, 2010). "However, leptin has been reported to stimulate proliferation and suppress apoptosis of hepatic cancer cells." (PMID 33671547, 2021). "Leptin- and IL-6-induced signaling via their respective receptors plays a major role not only in the control of energy homeostasis, but also under pathological conditions such as liver cancer beyond dispute." (PMID 30224299, 2018). "Leptin stimulates liver cancer development and progress, which could contribute to the high incidence of liver cancer in obese population." (PMID 26982332, 2016). "So far, no meta-analysis on leptin and liver cancer risk has been performed." (PMID 33256658, 2020). "Leptin was discovered to elicit the phosphorylation activation of STAT3, ERK1/2, and Akt in liver cancer cells, thereby enhancing cell proliferation and migration ability." (PMID 33799880, 2021).
Parkinson disease (17 papers, 2014 to 2025). A progressive degenerative disorder of the central nervous system characterized by loss of dopamine producing neurons in the substantia nigra and the presence of Lewy bodies in the substantia nigra and locus coeruleus. "Protective actions of leptin have been observed in several neurodegenerative models that replicate key pathological features of Parkinson’s disease and AD." (PMID 33440796, 2021). "Given the accumulating evidence of the various roles that leptin plays in the etiology and progression of Parkinson’s disease, which includes its ability to modulate neuroinflammation, it is imperative to conduct further studies that validate leptin and other adipokines as potential therapy target." (PMID 37233709, 2023). "As the statistically significant decrease of leptin was observed even at early stage of the disease, it would be interesting to explore whether leptin may be a potential biomarker for Parkinson’s disease, potentially aiding in earlier diagnosis or disease monitoring." (PMID 37233709, 2023). "Leptin maintains cell survival in neuronal SH-SY5Y cells by maintaining ATP levels and mitochondrial membrane potential to resist MPP+ toxicity (Parkinson’s disease model)." (PMID 39478700, 2024). "In various models of Parkinson’s disease (PD), the viability of dopaminergic neurons treated with either 6-OH dopamine or MPTP is significantly enhanced after treatment with leptin." (PMID 30386207, 2018).
triple-negative breast carcinoma (17 papers, 2011 to 2025). An invasive breast carcinoma which is negative for expression of estrogen receptor (ER), progesterone receptor (PR), and human epidermal growth factor receptor 2 (HER2). "Autophagy also contributed to leptin-induced glycolytic ATP production but only in triple-negative breast cancer cells." (PMID 38228661, 2024). "In both triple-negative breast cancer cell lines, the change in morphology was similar with all leptin concentrations used." (PMID 38228661, 2024). "Our data agree with the previous evidence and demonstrates that leptin not only enhances mitochondrial function and ATP production in hormone receptor-positive cells but also in triple-negative breast cancer cells." (PMID 38228661, 2024). "We used ER+/PR+ and triple-negative breast cancer cell lines treated with leptin, autophagy inhibition, or mitochondrial metabolism inhibitors." (PMID 38228661, 2024). "Some of these leptin antagonists have been seen to efficiently arrest the leptin-induced cell-cycle progression at the S-phase in triple-negative breast cancer (TNBC)." (PMID 35681689, 2022). "Further, leptin signaling was reported to maintain the stemness in triple negative breast cancer cells via upregulating the self-renewal transcription factors such as SOX2, OCT4 and NANOG via STAT3 signaling." (PMID 34588926, 2021). "Additionally, we demonstrate for the first time that leptin increased glycolytic ATP production in triple-negative breast cancer cells." (PMID 38228661, 2024). "Additionally, in triple-negative breast cancer cells, autophagy regulated mitochondrial metabolism, glycolytic ATP production and leptin-enhanced cell migration and invasion." (PMID 38228661, 2024). "Also, activated STAT3 seems to be crucial for the activation of CSC maintenance by leptin signaling in triple negative breast cancer." (PMID 31380268, 2019). "So, we describe a possibility to modulate cancer cell metabolism by regulating autophagy or to prevent leptin-induced cell migration by autophagy and/or OXPHOS inhibition in triple-negative breast cancer cells." (PMID 38228661, 2024). "Leptin induced autophagy in hormone receptor-positive cells but not in triple-negative breast cancer cells." (PMID 38228661, 2024). "In MDA-MB-231 triple negative breast cancer cells, which are known to have a high invasive capacity, leptin did not induce autophagy neither induced changes in proliferation or apoptosis, but increased cell migration, in agreement with previous reports." (PMID 33763424, 2021). "Thus, it has been described bidirectional crosstalk between leptin and IGF-1 signaling, resulting in the activation of EGFR to promote proliferation and migration of triple negative breast cancer cells." (PMID 31380268, 2019). "In a model triple-negative breast cancer cell line MDA-MB-231, the peptide antagonist Allo-aca at 1 pM–100 nM concentrations proved to antagonize the mitogenic effects of leptin in a concentration-dependent manner without interfering with MDA-MB-231 proliferation in the absence of native leptin." (PMID 34356668, 2021).
airway hyperresponsiveness (16 papers, 2012 to 2025). "Furthermore, leptin negatively modulates regulatory T cells and increases Th1 proliferation (leading to increased interferon-γ production); both of these effects are associated with airway hyperresponsiveness and airflow obstruction." (PMID 29975721, 2018). "Changes in adipose-derived inflammatory cytokines such as tumor necrosis factor-α, leptin, and adiponectin have the capacity to promote airway hyperresponsiveness." (PMID 36750832, 2023). "Subsequent studies relating to animal models support the role of leptin in increasing inflammatory cell infiltration, airway hyperresponsiveness, and inflammatory responses." (PMID 36551211, 2022). "Leptin, either applied exogenously or upregulated via a high fat diet in mice, promotes type 2 lymphocyte responses and airway hyperresponsiveness, and there is evidence that this requires activation of the IRE1α/Xbp-1 pathway in T cells." (PMID 30978945, 2019). "In mice leptin has been shown to enhance airway hyperresponsiveness, suggesting an immunomodulatory role." (PMID 24529685, 2014). "Leptin and adiponectin are also involved in airway hyperresponsiveness and inflammation." (PMID 38365763, 2024). "Leptin can aggravate airway hyperresponsiveness, while adiponectin can alleviate it." (PMID 38365763, 2024). "Leptin also appears to promote airway hyperresponsiveness in obese mice in a Th17 dependent manner." (PMID 30978945, 2019). "Instead, effects of leptin on the innate immune system might have led to the observed increase in airway hyperresponsiveness." (PMID 24288549, 2013). "These lipid-lowering agents attenuated airway hyperresponsiveness, macrophages in BALF, lung fibrosis, serum leptin, free fatty acids, TGF-β1, IL-1β, IL-6, and IL-17a in the lung." (PMID 38762465, 2024). "Sex-dependent differences are present in HDM-induced airway hyperresponsiveness, mucus production, and TGF-β1 levels with evidence of leptin-specific effects." (PMID 35610699, 2022). "Relationship between body composition and systemic inflammation (leptin, CRP), airway inflammation and airway hyperresponsiveness in females." (PMID 22296721, 2012). "Relationship between body composition and systemic inflammation (leptin, CRP), airway inflammation and airway hyperresponsiveness in males." (PMID 22296721, 2012). "Greater omental adipose tissue expression of leptin was also strongly related to airway hyperresponsiveness (i.e., lower methacholine PC20 values), while serum leptin concentrations were not similarly associated." (PMID 24288549, 2013). "However, neither BAL eosinophils nor Th2 cytokines were affected by leptin treatment, suggesting that leptin dependent modifications in airway hyperresponsiveness were independent of effects on T cells." (PMID 24288549, 2013).